ABCG2 (ATP binding cassette subfamily G member 2 (JR blood group))
Diseases named in the same sentence as ABCG2 in open-access papers (continued):
Sharing a sentence is not in itself a finding about the gene and the disease.
pancreatic cancer (continued). "Higher ABCG2 expression has been observed in various CSCs from lung, pancreas, and liver, and is co-expressed with CD133 in melanoma and pancreatic cancer cell lines." (PMID 27825361, 2016). "SP cells isolated from the PANC1, pancreatic cancer cell line, have been found to express both ABCB1 and ABCG2." (PMID 26649310, 2015). "Baseline characteristics of 140 patients with non-resectable pancreatic cancer treated with gemcitabine and nab-paclitaxel, distributed according to tumor expression of ABCG2." (PMID 40548120, 2025). "We performed both luciferase reporter and ChIP assays to confirm that FOXP1 binds to the ABCG2 promoter, which has not been previously reported in pancreatic cancer." (PMID 40169859, 2025). "Dose of chemotherapy according to ABCG2 expression in tumors of 140 patients with non-resectable pancreatic cancer treated with gemcitabine and nab-paclitaxel." (PMID 40548120, 2025). "Interestingly, in the pancreatic cancer cells PANC-1, a clear dissociation between ABCG2 protein levels in EVs and cell lysates was reported." (PMID 38612927, 2024). "Next we investigated the potential effect of ABCG2 inhibitors (Ko143) and ABCB1 inhibitors (verapamil) on the intracellular accumulation of gemcitabine to further confirm ABC transporter function on gemcitabine efflux in pancreatic cancer cells." (PMID 31652737, 2019). "Furthermore, pancreatic cancer cells which express high levels of CD133, c-Met, or ABCG2 exhibit drug resistance." (PMID 28032597, 2017). "Encouraging results have been reported by recent studies showing that pancreatic carcinoma could be inhibited by controlling several biomarkers such as SMAD4, CXCR2, ABCG2 and Kras." (PMID 28077929, 2017). "In order to determine how widespread expression of ABCG2 might be in PDAC, we obtained previously published microarray data from 22 pancreatic cancer cell lines and compared the expression of ABCG2 to that of MDR-1." (PMID 26859746, 2016). "CSCs derived from pancreatic tumour cells have higher expression of ABCB1 and ABCG2." (PMID 27825361, 2016). "Cancer stem cells markers such as ALDH1A1, ABCG2, and nestin are highly expressed in metastatic cancer cells compared to non-metastatic cancer cells in animal models of pancreatic cancer." (PMID 26029109, 2015). "ABCG2, as a determining factor of side population, its expression in normal pancreas is absent or low but high in human pancreatic cancer cells." (PMID 24587996, 2014). "Therefore, we next assessed whether coix seed extract could modulate the drug efflux effect regulated by the ATP binding cassette transporters ABCG2 and ABCB1 in pancreatic cancer cells in vitro and in vivo." (PMID 31652737, 2019). "Therefore, ABCG2-high pancreatic CSCs might be well targeted by 5-ALA PDT using an ABCG2 inhibitor, and this approach could be another way to target SHH signaling-activated pancreatic cancer cells." (PMID 31083682, 2019). "Second, we used PDAC cell lines rather than patient-derived pancreatic cancer cells and did not confirm the relationship between NRF2 and target proteins, such as ABCG2, in vivo." (PMID 32629871, 2020). "The addition of IL-17A to pancreatic cancer cells did not increase the subpopulation of cells expressing the typical stem cell markers such as CXCR4, ABCG2, and CD44." (PMID 32210079, 2020).
glioma (74 papers, 2009 to 2025). A benign or malignant brain and spinal cord tumor that arises from glial cells (astrocytes, oligodendrocytes, ependymal cells). "ABCG2 expression is associated with glioma cell stem-like properties, including self-renewal and differentiation potential, which are reasons for tumor recurrence and resistance." (PMID 40370575, 2025). "To further explore the function of ABCG2 under different oxygen concentrations in glioma cells, we performed gain-and loss-of-function experiments." (PMID 40370575, 2025). "High levels of ABCG2 expression are often associated with more aggressive tumor phenotypes and poorer outcomes, which highlights its potential as a prognostic marker for glioma patients." (PMID 38542090, 2024). "A number of ABCG2 regulators already introduced in the clinic, such as telmisartan and febuxostat, remain to be tested in glioma PDT association." (PMID 39201395, 2024). "There are several potential mechanisms underlying the implications of the interplay between ATRX mutation status and ABCG2 expression in gliomas." (PMID 38542090, 2024). "In our cohort, we presented a significant association between Ki67 expression and ABCG2 profile in human gliomas." (PMID 38542090, 2024). "The association between ATRX and ABCG2 levels in brain tumors, particularly in gliomas, highlights the complex interplay of genetic alterations and drug resistance mechanisms that influence tumor behavior and therapeutic outcomes." (PMID 38542090, 2024). "In this study, we aimed to explore the expression of ABCG2 and its association with glioma grade and tumor progression, as well as to evaluate the expression of ABCG2 as a potential predictive factor for tumor progression and patient survival." (PMID 38542090, 2024). "Previous work from our laboratory determined that ROCK2 was the important mediator of acquired resistance to TMZ in glioma cells and the mechanism underlying the regulation of ABCG2, which was functions as a high-capacity drug efflux transporter." (PMID 35145081, 2022). "ABCG2 (ATP-binding cassette super-family G member 2) is a membrane-associated protein also a known cancer stem cell marker in gliomas." (PMID 35008722, 2021). "ABCG2 expression has been linked to the stem-like properties of glioma cells, including self-renewal and differentiation potential, which are characteristic of GSCs and most likely responsible for tumor initiation, recurrence, and resistance to conventional therapies." (PMID 38542090, 2024). "Additionally, the upregulation of ABCG2 in the vasculature was linked to the efflux of drugs from the brain, contributing to the chemoresistant nature of gliomas." (PMID 38542090, 2024). "Sixty glioma-associated targets were associated with CHR, such as MDR transporters (ABCB1, ABCC1, ABCG2), cyclin-dependent kinases (CDK1, CDK6), matrix metalloproteinases (MMP2, MMP9, MMP12), and genes related to inflammation or oxidative stress (NOS2, NOX4)." (PMID 40963691, 2025). "The results indicated that ABCG2 was highly expressed in the hypoxic microenvironment of glioma cells." (PMID 40370575, 2025). "This study confirmed that hyperbaric oxygen can inhibit ABCG2 expression through HIF1α and HIF2α, thereby promoting the proliferation and chemosensitization of gliomas." (PMID 40370575, 2025). "In conclusion, HBO can affect the progression of glioma by regulating ABCG2 expression through HIF1/2α." (PMID 40370575, 2025). "In human glioma, ABCG2 is overexpressed in CSCs, underscoring the necessity for a deeper understanding of its biological and clinical implications." (PMID 38542090, 2024). "Patients with glioma tumors with higher ABCG2 expression exhibited poorer survival rates following chemotherapy or radiotherapy treatment." (PMID 38542090, 2024). "The intensity and pattern of ABCG2 staining have been correlated with the grade of malignancy in gliomas." (PMID 38542090, 2024).
glioma (continued). "By assessing ABCG2 expression in the tumor vasculature, clinicians can better gauge the aggressiveness of gliomas and tailor treatment strategies accordingly." (PMID 38542090, 2024). "In general, IHC studies have been instrumental in localizing and quantifying ABCG2 expression within tumor tissues, revealing a heterogeneous distribution of ABCG2 within glioma tissues." (PMID 38542090, 2024). "The implications of ABCG2 expression in gliomas extend beyond resistance mechanisms, as its presence has been correlated with tumor grade and patient prognosis." (PMID 38542090, 2024). "Animal studies, particularly those utilizing rodent models of glioma, have been instrumental in elucidating the role of ABCG2 in the BBB and the treatment of gliomas." (PMID 38542090, 2024). "These interactions highlight the complexity of ABCG2 role in glioma and underscore the need for comprehensive strategies targeting multiple pathways to overcome drug resistance." (PMID 38542090, 2024). "Given these complexities, the objective of this paper was to explore the expression of ABCG2 in human gliomas and its implications for treatment strategies and patient outcomes." (PMID 38542090, 2024). "Our research clarified the expression of ABCG2 in human gliomas and suggests possible implications for treatment strategies and patient outcomes." (PMID 38542090, 2024). "Studies using glioma xenografts in mice showed that ABCG2 contributes to the formation and maintenance of the BBB, thereby influencing drug delivery and therapeutic outcomes in patients with glioma." (PMID 38542090, 2024). "The heme biosynthetic pathway activity was greater in fluorescent gliomas with the upregulation of PpIX-generating enzymes and decreased PpIX efflux mediated by the ABCG2 membrane pump." (PMID 38672647, 2024). "This study scrutinized the relationship between ABCG2 expression and glioma grade and the role of ABCG2 in the process of glioma progression, aiming to evaluate ABCG2 expression as a predictive factor of tumor progression and patient survival." (PMID 38542090, 2024). "The localization of ABCG2 within the tumor vasculature significantly complicates the landscape of glioma treatment." (PMID 38542090, 2024). "Conducted at Dubrava University Hospital, Zagreb, Croatia, the study analyzed 152 glioma specimens from 2013 to 2022, assessing ABCG2 expression alongside standard clinical markers." (PMID 38542090, 2024). "Most previous studies explored ABCG2 expression in grade IV glioma, as well as differences in expression in low- and high-grade tumors in animal models." (PMID 38542090, 2024). "The exploration of ABCG2 inhibitors used in conjunction with traditional chemotherapy represents a promising approach to surmount drug resistance in gliomas." (PMID 38542090, 2024). "Another study on brain tumor stem cells and glioma cells (A172) proved that melatonin in combination with chemotherapeutic agents influences the hypermethylation of the promoter of the ABCG2/BCRP gene responsible for multidrug resistance and tumor recurrence." (PMID 37371885, 2023). "According to our data, we found distinct increases in the 5-ALA metabolizing enzymes CPOX, PPOX, and FECH and decreases in the PpIX exporting transporter ABCG2 on protein level in fluorescing glioma samples." (PMID 35665365, 2022). "Breast cancer resistance protein (BCRP, also known as ABCG2) is related to the grade and chemoresistance of glioma." (PMID 35740330, 2022). "To this end, we compared the mRNA as well as protein expression levels of CPOX, PPOX, FECH and ABCG2 in glioma tissue samples with presence of strong 5-ALA induced fluorescence during surgery to non-fluorescing glioma samples." (PMID 35665365, 2022). "Our data indicate that heme biosynthesis pathway activity in general is enhanced in fluorescing gliomas with upregulation of PpIX generating enzymes and decreased ABCG2 mediated PpIX efflux outweighing the also increased further metabolization of PpIX to heme." (PMID 35665365, 2022).
glioma (continued). "In the present study, the clinicopathological features of CRNDE were assessed and the role of CRNDE in glioma cell viability, colony formation, proliferation, apoptosis, autophagy and ABCG2 expression induced by TMZ were performed in vitro and in vivo." (PMID 34454479, 2021). "Overall, these data in vivo further verified that the altered expression of CRNDE played a crucial biological role in chemosensitivity to TMZ in glioma and potentially related with the regulation of ABCG2." (PMID 34454479, 2021). "Our previous studies reported that nicardipine enhanced mitoxantrone-induced cytotoxicity against glioma through competitive inhibition of ABCG2, confirming the sensitizing role of nicardipine with chemotherapeutic agent on gliomas." (PMID 33621205, 2021). "Combinations of MLT and temozolomide showed a significant synergistic toxic effect on BTSCs and A172 malignant glioma cells by downregulation of the ABC transporter ABCG2/BCRP." (PMID 32545820, 2020). "In glioma, the most relevant ABC transporter proteins are p-glycoprotein (ABCB1), MDR-associated protein-1 (ABCC1), and breast cancer resistance protein (ABCG2)." (PMID 30123112, 2018). "Previous research showed that 40-50% WHO III and WHO IV glioma tissues and 100% U251 GSCs overexpressed ABCG2." (PMID 28591733, 2017). "We analyzed the role of ABCG2, a drug transporter, in determining the sensitivity of glioma stem cells (GSCs) to demethoxycurcumin (DMC)." (PMID 28591733, 2017). "Accompanied by downregulation of CD133/ABCG2 and upregulation of glial fibrillary acidic protein, bELE was shown to decrease the formation of spheres and inhibit the proliferation of glioma stem cells both in vitro and in vivo." (PMID 28297578, 2017). "Some reports suggest that ABCG2 regulates self-renewal and stem cell marker expression in radiation-resistant glioma cells and NSCLC cell lines." (PMID 28219421, 2017). "In the following sections, we review the potential contributions of ABCB1 and ABCG2 in gliomas and medulloblastoma." (PMID 29186899, 2017). "Another study evaluated ABCG2 status in 33 human primary glial tumors from patients with refractory epilepsy." (PMID 29186899, 2017). "Traditional studies have ascribed the chemoresistance of glioma to GSCs as a result of the higher expression of chemoresistance-related proteins, such as ABCG2 and MGMT3, 8, 11, 23–25." (PMID 28801626, 2017). "For example, miR-145 has been found to inhibit migration and invasion of gliomas stem cells by targeting ABCG2." (PMID 28977881, 2017). "Here, we show that ABCG2 can actively drive expression of stem cell markers and self-renewal in glioma cells." (PMID 27456282, 2016). "To test the contribution of ABCG2 as a driver of stemness, we generated human U87MG glioma cells overexpressing ABCG2, and isolated SP cells from this line in two steps to ensure a line with high ABCG2 activity." (PMID 27456282, 2016). "Our data demonstrate that characteristics of tumor stem cells are separable, and highlight ABCG2 as a potential driver of glioma stemness." (PMID 27456282, 2016). "Similar results were obtained using the U87 human glioma cell line, suggesting that indeed, ABCG2 regulation of stem cell marker gene expression (other than Hes1) can be mediated by MEF." (PMID 27456282, 2016). "A previous glioma drug study was performed using a chitosan-hyaluronic acid (HA) scaffold, which induced weak drug resistance corresponding to increased ABCG2 expression." (PMID 27486877, 2016). "miR-145 is reported to inhibit MDR1 in intestinal cells and ABCG2 in glioma cells as we all as in corneal cells." (PMID 26425114, 2015). "Beside MGMT, the drug efflux transporters ABCB1 and ABCG2 are thought to affect survival of glioma patients due to their role in drug resistance." (PMID 24380367, 2013).
glioma (continued). "ABCB1 was shown to be expressed both in low-grade glioma and high-grade glioma such as glioblastoma and ABCG2 was found to be expressed in glioma stem cells as well as in endothelial cells of the large vessels of glioma tissue." (PMID 24380367, 2013). "A further drug resistance gene we decided to analyze was ABCG2, because this efflux transporter was found to be expressed in glioma stem cells as well as in endothelial cells of the large vessels of glioma tissue." (PMID 24380367, 2013). "In glioma, ABCG2 expression is related with pathological grade, tissues differentiation and resistance to mitoxantrone." (PMID 23153066, 2012). "Overexpression of ABCG2/BCRP and other transporters, such as MRP1, is associated with lower intracellular CPT accumulation and poorer clinical response in multiple tumors, including breast, glioma, hepatocellular, and non-small cell lung cancers." (PMID 41304752, 2025). "This study aimed to scrutinize the relationship between ABCG2 expression and glioma grade, as well as the role of ABCG2 in the process of glioma grade progression, and try to detect the expression of ABCG2 as a potential predictive factor for tumor progression and patient survival." (PMID 38542090, 2024). "This efflux activity of ABCG2 at the BBB underscores the need for innovative strategies that can either bypass or inhibit ABCG2 function to enhance the delivery of chemotherapeutic drugs to gliomas." (PMID 38542090, 2024). "Therefore, the ABCG2 profile and expression levels serve as significant markers for both the biological behavior of gliomas and their response to therapeutic interventions." (PMID 38542090, 2024). "The prognostic value of ABCG2 expression in gliomas has been increasingly recognized." (PMID 38542090, 2024). "Some reports indicate that glioma cells with high ABCG2 expression accumulate less photosensitizer, so ABCG2 may be responsible for the poor response to PDT." (PMID 39201395, 2024). "Understanding the relationship between ATRX status and ABCG2 expression could provide insights into the prognosis of glioma patients and inform treatment strategies." (PMID 38542090, 2024). "By integrating ABCG2 profiling into clinical practice, oncologists can better tailor treatment plans, potentially improving survival rates and quality of life for those affected by not only gliomas, but also all other human cancers." (PMID 38542090, 2024). "Furthermore, the ABCG2 profile’s predictive value for therapy outcomes highlights its importance in personalized medicine approaches for glioma patients." (PMID 38542090, 2024). "Additionally, the use of RNA interference technology to knock down ABCG2 expression has yielded promising results in preclinical models, further supporting the therapeutic potential of targeting ABCG2 in glioma treatment." (PMID 38542090, 2024). "ABCG2 may serve as a marker of angiogenesis and vascular abnormalities within tumors, predicting glioma progression and treatment response." (PMID 38542090, 2024). "Activation of AKT has been shown to increase ABCG2-driven SP+ glioma tumor-initiating CSC." (PMID 34230478, 2021). "Taken together, these data demonstrated that knockdown of lncRNA CRNDE could enhance chemosensitivity to TMZ, inhibit cell viability, decrease cell proliferation, facilitate cell apoptosis, and reduce the expression of ABCG2 in glioma cells." (PMID 34454479, 2021). "In addition, overexpression of NEFL increases the chemosensitivity of glioma cells to TMZ treatment by downregulating the multidrug resistance factors ABCG2, ABCC3, and ABCC5, which are ABC transporters and function as xenobiotic transporters." (PMID 33324542, 2020). "The combination of MLT and a chemotherapeutic agent exhibited a potential synergistic toxic effect against A172 malignant glioma cells and brain tumor stem cells via downregulating the expression and function of adenosine triphosphate-binding cassette transporter ABCG2/BCRP." (PMID 32545820, 2020).